JAK2 (Janus kinase 2)
Diseases named in the same sentence as JAK2 in open-access papers (continued):
Sharing a sentence is not in itself a finding about the gene and the disease.
breast cancer (continued). "STAT3 can be phosphorylated by activated JAK2 induced by IL-6, which is a key mediator of the inflammatory response and functions as a crucial regulator in the progression of breast cancer." (PMID 31186039, 2019). "Nevertheless, in our model system, exposure of breast cancer cells to MH leads to a rapid loss of >80% of activated p-STAT3 protein, which is also associated with decreased gp130 and p-JAK2 levels." (PMID 31491838, 2019). "In breast cancer, JAK2/STAT5 activation is associated with resistance to PI3K/mTOR inhibitors, and combination therapy targeting JAK2/STAT5 and PI3K/mTOR was proposed to overcome this resistance." (PMID 31601188, 2019). "It has been shown that leptin promotes the development and progression of breast cancer neoplastic cells by activating the JAK2/STAT3 pathway." (PMID 31380268, 2019). "A cross-talk between STAT5 (activated by JAK2) and Akt1 has also been reported that is essential for progression of breast cancer." (PMID 31681603, 2019). "JAK2 is a transcriptional activator of both PD-1 ligands and amplification of this locus provides a distinct molecular subtype in breast cancer, gastric cancer and lymphomas." (PMID 30417146, 2018). "Further studies showed that combinational drug therapy targeting Jak2-STAT5b signaling inhibited breast cancer metastasis." (PMID 30558204, 2018). "Here, we showed that GRAMD1B expression is upregulated on IL-6 but downregulated upon treatment with the JAK2 inhibitor AG490 in the breast cancer MDA-MB-231 cells." (PMID 29934528, 2018). "Upstream of Jak2 and STAT3, IL6 is also linked to breast cancer metastasis: IL6 expression was found to be higher at the invasive leading edge of human primary breast cancer cells." (PMID 30558204, 2018). "PTP1B acts a negative regulator of both STAT5 and Jak2 activation in invasive breast cancer cell lines." (PMID 30558204, 2018). "In particular, Jak2-STAT5b signaling is often over-activated during tumor cell proliferation and metastatic spread of breast cancer." (PMID 30558204, 2018). "In conclusion, we demonstrated that dimerization of EGFR and HER2 induced ACTA2 expression through a JAK2/STAT1-dependent signaling pathway that triggers breast cancer cell motility." (PMID 28881584, 2017). "The hGH/JAK2/STAT3 signaling transduction pathway has been identified as a critical signaling pathway in breast cancer and HCC." (PMID 28617312, 2017). "IL-6 is a direct regulator of breast CSC self-renewal and IL-6/JAK2/STAT3 pathway is more active in CD44(+)CD24(-/low) breast cancer cells compared with other tumor cell types and its inhibition blocks the growth of xenografts." (PMID 28270211, 2017). "Marotta and the colleagues reported that the JAK2/STAT3 signaling pathway was required for growth of CD44+CD24− stem cell-like breast cancer cells." (PMID 28591704, 2017). "Its overexpression inhibits cell proliferation and promotes apoptosis in breast cancer cells by inhibiting Jak2." (PMID 27832764, 2016). "JAK2/STAT3 promotes self-renewal of breast cancer stem cells, CD24−CD44+ is a marker for breast cancer stem cells." (PMID 26883017, 2016). "Activation of JAK2/STAT3 pathway preferentially promotes the self-renewal of C24−CD44+ breast cancer stem cells." (PMID 26883017, 2016). "In conclusion, our study indicates that JAKi enhance metastasis in experimental models of breast cancer by inhibiting NK-cell functions, and that JAK2 has an essential role in controlling NK-cell-mediated tumour immunosurveillance." (PMID 27406745, 2016). "For example, overexpression of hsa-miR-204 inhibited the proliferation and promoted the apoptosis in breast cancer cells by targeting JAK2." (PMID 27253583, 2016). "In these studies we also found ERBB2/HER2, a member of epidermal growth factor receptor family which is overexpressed in about 10% of the ER+ breast cancers phosphorylated and activated by JAK2 induced by PRL through PRLR." (PMID 27564112, 2016).
breast cancer (continued). "We use T47D and TMX2-28 breast cancer cells stably overexpressing GFP, PAK1 WT, or tyrosyl phosphorylation-deficient mutant of PAK1 in which the three JAK2 phosphorylation sites have been mutated to phenylalanine (PAK1 Y3F)." (PMID 27542844, 2016). "The positive correlations between STIP1 and JAK2 expression were also seen in other cancer types, including hepatocellular carcinoma and breast cancer." (PMID 27409672, 2016). "In the same context, PRL/PRLR signaling has the ability to promote progression and invasion in breast cancer through independent pathways to JAK2/STAT5, such as c-Src, FAK and MAPK." (PMID 26346346, 2015). "Previous in vitro studies of a 9p amplicon in a small panel of established breast cancer cell lines excluded JAK2, PD-L1, and PD-L2 loci from the SRO reported." (PMID 26317899, 2015). "Mouse mammary cancer cells with intact Jak2 (Jak2+/+) resulted in up regulation of Lmo2 and Nanog in MUC16-Cter dependent manner and this dependence was abrogated in cells genetically deleted for Jak2 (Jak2−/−)." (PMID 25691062, 2015). "Several kinases have been implicated in maintaining STAT3 activity in breast cancer, including EGFR, JAK2, and Src." (PMID 25699542, 2015). "A more pronounced effect of MUC16-Cter is observed in LMO2 expression compared to NANOG in T3M4 and Jak2+/+ mammary tumor cells." (PMID 25691062, 2015). "Further investigation indicated that the IL-6/JAK2/STAT3 pathway was preferentially active in CD44+CD24− breast cancer stem cells, and inhibition of JAK2 decreased the number of cancer stem cell number and blocked the growth of xenografts in mice." (PMID 24995504, 2014). "Marotta and coworkers targeted the JAK2/Stat3 signaling pathway for specific breast cancer therapies by highlighting the difference between distinct breast cancer cell types." (PMID 23401782, 2013). "Rather, progesterone can rapidly activate the Src/Ras/MAPK, PI3 kinase/Akt, and JAK2/Stat3 signaling pathway in breast cancer." (PMID 23484104, 2013). "The JAK2/STAT3 signaling pathway is preferentially activated in CD44+ breast cancer stem cell population over other cell populations, and hyaluronic acid synthase 1 (HAS1) is a STAT3 signaling-related molecule in basal-like breast cancer." (PMID 23326564, 2013). "They found that the IL-6/JAK2/Stat3 pathway was preferentially active in CD44+ CD24− breast cancer cells compared to other tumor cell types." (PMID 23401782, 2013). "Jak1 was reported to be activated by PRL signaling in human breast cancer lines and cooperate with Jak2 to enhance signaling pathways downstream of PRL receptors, including Stat5, Stat3 and Erk activation." (PMID 23758962, 2013). "This is consistent with recent results demonstrating that the cytokine IL-6 is able to stimulate breast cancer stem cells and JAK2/STAT3 signaling pathway is required for growth of breast cancer stem cells." (PMID 24376586, 2013). "In breast cancer, miR155 enhanced the JAK2/STATS signalling pathway and transfection of miR155 mimics promoted MDA-MB-231 and MCF-7 cell proliferation." (PMID 23284982, 2012). "Overexpressed in breast cancer, it augments cell proliferation by interacting with JAK2 and inhibiting the apoptotic process through downregulation of TRAIL." (PMID 22937096, 2012). "A similar association between JAK2 and the receptor has been reported in HEK293, H1299 lung adenocarcinoma and MCF7 human breast carcinoma cells." (PMID 22697788, 2012). "These IC50 values are comparable to the published data in breast cancer and Jak2/MPL mutant cells (~100 nM), but significantly less than Bcl-6-dependent lymphoma cells ( > 1 μM)." (PMID 20977755, 2010).
breast cancer (continued). "Herein, we exhaustively reviewed the current tools available to target this pathway in clinical trials and we offer several perspectives to gain further insight into the role of JAK2 in breast cancer and more particularly in the resistance to endocrine therapy in hormone-dependent breast cancers." (PMID 41463071, 2025). "In addition, a large number of studies have confirmed that JAK2/STAT3 signaling plays an important role in breast cancer progression, regulating key processes including cell proliferation, survival and immune escape." (PMID 40351419, 2025). "We also demonstrated the essentiality of its catalytic activity in suppressing breast cancer lung metastasis, as evidenced by the observation that PTPRO with an active site mutation failed not only to dephosphorylate JAK2 and YAP but also to inhibit breast cancer lung metastasis." (PMID 40016288, 2025). "Moreover, dual targeting strategies—such as simultaneous inhibition of TrkA and JAK2—have demonstrated synergistic effects in preclinical breast cancer models." (PMID 41226473, 2025). "Additionally, another study indicated that methyl selenite significantly inhibits breast cancer growth by suppressing the JAK2/STAT3 signaling pathway." (PMID 40821907, 2025). "Collectively, circRNA-14,052 knockdown could inhibit the breast cancer progression in vitro via miR-214-3p/IKBKB/IL-6/JAK2/STAT3 axis." (PMID 41044672, 2025). "A previous study reported that C15:0 could suppress IL-6-induced JAK2/STAT3 signaling in MCF-7/stem-like breast cancer cells." (PMID 40356914, 2025). "Additionally, HOXC10 contributes to breast cancer progression by activating the IL‐6/JAK2/STAT3 signaling axis." (PMID 39558881, 2024). "Moreover, functional assays uncovered the crucial role of CCT2 in breast cancer progression via the JAK2/STAT3 signaling pathway." (PMID 39079960, 2024). "The molecular docking of JAK2 with Ag atoms indicated a possible interaction that could reduce the involvement of JAK2 in breast cancer cells." (PMID 38779072, 2024). "Finally, studies also suggest that metformin can inhibit several STAT3-related signaling pathways known to be involved in breast cancer, including IL-6/JAK2/STAT3 signaling." (PMID 38543182, 2024). "Our data showed that this compound reduced the expression of IL-6 mRNA and STAT3, which promote proliferation, metastasis, invasion, and angiogenesis in breast cancers, and could result in the suppression of the NF-kB/IL-6/JAK2/STAT3 signaling pathway." (PMID 38673967, 2024). "Previous research has indicated that ZSWIM4 reduces the sensitivity of breast cancer cells to JAK2 inhibitor, and ZSWIM4 might play a role in the response to vitamin D treatment in colon tissues, although the underlying mechanism is not elucidated yet." (PMID 38951864, 2024). "Methylselenic acid inhibits breast cancer tumor growth by inhibiting JAK2/STAT3 pathway." (PMID 38872110, 2024). "Its supernatant could inhibit the autocrine secretion of IL-6 and the phosphorylation of JAK2/STAT3 in the breast cancer cell line MCF-758." (PMID 38395948, 2024). "For example, targeting JAK2/STAT3 signaling pathway has been utilized in breast cancer treatment." (PMID 36836069, 2023). "Also, TrkB induces cell survival of colon and breast cancer through the activation of ERK or JAK2/STAT3 signaling pathways." (PMID 37749450, 2023). "Preclinical studies have shown that specific JAK2 inhibitors can inhibit the growth of tumors in vivo, including pancreatic cancer, colorectal cancer, gastric cancer, liver cancer, lung cancer, ovarian cancer, and breast cancer." (PMID 36911202, 2023). "Activation of JAK2/STAT3 signaling facilitates the growth of breast cancer cells." (PMID 36674719, 2023). "Our previous reports indicated that MUC16 could induce the G2-M transition of breast cancer cells by interacting with Janus kinase 2 (JAK2), which in turn enhances the phosphorylation of STAT3 (Y705) and Aurora Kinase A." (PMID 36918912, 2023).
breast cancer (continued). "Additionally, via the NF-kB/IL-6/JAK2/STAT3 pathway inhibition in breast cancer cells, we recently demonstrated the anticancer activity of azilsartan." (PMID 36611978, 2023). "Our results from the Mayo Clinic Breast Cancer SPORE TMA identified an association of increased stromal TILs in those TNBCs (14%) with PDJ amplicons targeting PD-L1 and JAK2 (P < 0.01)." (PMID 36635351, 2023). "Also, this ligand reduces the sensitivity of breast cancer cells to apoptosis and drug resistance through the Jak2/STAT3 signaling pathway." (PMID 35684481, 2022). "Interestingly, an analysis of three independent cohorts NETHERLANDS, METABRIC and OSLOVAL concluded that JAK2 mRNA expression was protective in all types of breast cancer." (PMID 35053592, 2022). "In conclusion, the present study revealed, for the first time, the anti-proliferative, apoptotic, anti-migration and EMT inhibition activities of azilsartan against breast cancer cells through modulating NF-kB/IL-6/JAK2/STAT3/MMP9, TWIST/SNAIL/SLUG and apoptosis signaling pathways." (PMID 36431925, 2022). "We decided to look for possible binding motifs for Janus kinase 2 to investigate their anticancer activity on breast cancer, phosphoinositide-dependent kinase-1 to investigate their activity on prostate cancer, and human anaplastic lymphoma kinase to investigate their activity on lung cancer." (PMID 36364134, 2022). "MiR-101 also has a pro-apoptotic role in breast cancer via Janus Kinase 2 (JAK2)." (PMID 36497343, 2022). "Additionally, it was reported that pioglitazone, one of PPARγ agonists, inhibited breast cancer growth by regulating JAK2/STAT signaling pathway in vitro and in vivo." (PMID 33917914, 2021). "In addition, relevant studies presented the essential role of JaK2 in CDDP resistance in breast cancer and non-small cell lung cancer." (PMID 34307356, 2021). "CXCL3 promoted breast cancer cell proliferation through the JAK2/STAT3 signaling pathway." (PMID 34870709, 2021). "Additional research revealed that breast cancer stem cells stemness characteristics could be lost by JAK2/STAT3 signaling pathway blockage." (PMID 34900727, 2021). "STAT3, particularly phosphorylated by JAK2, is one of breast cancer clinical significance." (PMID 33672756, 2021). "Furthermore, the silencing of B7-H3 increased the sensitivity of multiple human breast cancer cell lines to paclitaxel by abrogating Jak2/Stat3 phosphorylation." (PMID 32127943, 2020). "Therefore, Jak2 is a potential therapeutic target for FGFR1 amplified breast cancer, especially in the context of obesity." (PMID 33019728, 2020). "Specifically, leptin is thought to promote breast cancer through the activation of Janus kinase 2/Signal Transducers and Activators of Transcription 3 (Jak2/Stat3), mitogen-activated protein kinase (MAPK) and Phosphatidylinositol-3-kinase/Protein kinase B (PI3K-AKT)." (PMID 33019728, 2020). "FGFR1 and Jak2 have both been observed to be upregulated in breast cancer." (PMID 33019728, 2020). "Finally, we found an inverse correlation between JAK2 and PDGFRβ mRNA levels in both breast cancer TCGA and METABRIC data." (PMID 30777101, 2019). "JAK2 silencing inhibited the formation of breast cancer mammospheres." (PMID 31658701, 2019). "JAK2/STAT3 signaling pathway plays a crucial role in the growth of breast cancer cells." (PMID 31540495, 2019). "Moreover, although not statistically significant, we found a pattern of poor survival in TCGA breast cancer patients expressing high PDGFRβ with low JAK2 levels compared to patients expressing low PDGFRβ with high JAK2 levels (HR:1.507, logrank: 0.00804)." (PMID 30777101, 2019).
breast cancer (continued). "Recent report suggests that JAK2 inhibition increases metastasis burden by suppressing the function of NK cells in breast cancer and off-targets effects of Nilotinib on various immune cells may contribute towards its anti-tumor efficacy." (PMID 30777101, 2019). "Therefore, to investigate the resistance mechanisms mediated by JAK2 inhibition in our setting, we developed a machine-learning (ML) model to predict the clinical response to JAK2 inhibition in breast cancer patients." (PMID 30777101, 2019). "Preclinical data support a role for the IL-6/JAK2/STAT3 signaling pathway in breast cancer." (PMID 29761158, 2018). "Another example is lncRNAs associated with breast cancer brain metastases (lnc-BM), which binds to JH2 domain of JAK2 protein thus mediate oncostatin-M and signal transducer and activator of transcription 3 (STAT3) phosphorylation by increasing JAK2 kinase activity." (PMID 30018955, 2018). "In addition, the HER2-STAT3 network has been shown to contribute to the aggressive phenotype of breast cancer stem cells, and the JAK2/STAT3 signaling pathway is required for the growth of CD44+CD24− stem cell-like breast cancer cells in human tumors." (PMID 29636641, 2018). "Thus, our results showed that JAK2 inhibition is a rational strategy to combat chemoresistance in breast cancer." (PMID 29383118, 2017). "Whereas ERα + breast cancer cells cultured in low density/compliant three-dimensional collagen I matrices respond to PRL predominantly by activating physiological JAK2/STAT5 signals, high density/stiff matrices shift PRL responses to pathological ERK1/2 signals and increase invasiveness." (PMID 28103936, 2017). "C14orf166 interacts with ninein to block the phosphorylation of ninein catalyzed by GSK-3β, suggesting C14orf166 may inhibit ninein, and activate JAK2 to promote breast cancer progression, but this speculation remain to be confirmation." (PMID 26883017, 2016). "Prolactin receptor is found in up to 80% of breast cancer cells, where it couples to several signaling pathways, including Janus Kinase (JAK)-2/Signal Transducer and Activator of Transcription (STAT)-5, mitogen-activated protein kinase (MAPK), and phosphatidylinositol-3-OH-kinase (PI3K)." (PMID 26733941, 2015). "Members of the interleukin-6 (IL-6) family, which are induced in a paracrine/autocrine fashion in breast cancer, mediate the activation of the Janus Kinase 2 (JAK2) and of the signal-transducer and transcription factor 3 (STAT3) promoting the expansion of mammary CSCs." (PMID 25774169, 2015). "Moreover, NDRG2 expression negatively regulates JAK2/STAT3 through the regulation of the suppressor of cytokine signaling 1 gene in breast cancer cells." (PMID 25061501, 2014). "In primary breast cancer, interleukin-6 (IL-6) induced activation of its downstream effectors, JAK2 and STAT3, and this signaling played a critical and pharmacologically targetable role in orchestrating the composition of the tumor microenvironment that promotes growth, invasion, and metastasis." (PMID 25405202, 2014). "In addition to direct transcriptional effects mediated by nuclear PR, other authors have shown that progestins can rapidly activate the Src/Ras/MAPK, PI3 kinase/Akt, and JAK2/Stat3 signaling pathway in breast cancer and mammary epithelial cells." (PMID 23484104, 2013). "We cannot exclude that PRLR signaling is still capable of promoting breast cancer progression and invasion through Jak2/Stat5-independent pathways such as c-Src, FAK, and MAP kinases and beyond towards proliferative effects; thus, other PLR roles are currently being diligently investigated." (PMID 24148306, 2013).